SLC34A1 (solute carrier family 34 member 1)
Description:
Involved in actively transporting phosphate into cells via Na(+) cotransport in the renal brush border membrane. The cotransport has a Na(+):Pi stoichiometry of 3:1 and is electrogenic (By similarity).
Synonyms: NPT2; SLC17A2; NAPI-3; NPTIIa; SLC11; FRTS2; HCINF2; NPHLOP1
Tractability: Small molecule: a high-quality ligand is known. Antibody: UniProt places it where antibodies can reach, with high confidence; its Gene Ontology location is reachable by antibodies, with high confidence; UniProt predicts a signal peptide or a membrane-spanning region. PROTAC: a small molecule that binds it is known.
Target class: Transporter; SLC34 family of sodium phosphate co-transporters; Electrochemical transporter; SLC superfamily of solute carriers
Chemical probes: PF-06869206 (high quality)
Gene: Protein-coding gene on chromosome 5 (177,379,235 to 177,398,848, forward strand). Ensembl gene ENSG00000131183.
Subcellular location: Apical cell membrane; Cell membrane
Subcellular location (Human Protein Atlas): Nuclear speckles; Plasma membrane; Cytosol; Mitotic spindle; Nucleoplasm
Pathways (Reactome):
Disease: Defective SLC34A1 causes hypophosphatemic nephrolithiasis/osteoporosis 1 (NPHLOP1)
Metabolism of proteins: Surfactant metabolism
Transport of small molecules: Type II Na+/Pi cotransporters
Gene Ontology:
Molecular function: protein binding; sodium:phosphate symporter activity; identical protein binding; PDZ domain binding; protein-containing complex binding
Biological process: phosphate ion homeostasis; phosphate ion transport; response to cadmium ion; response to lead ion; response to mercury ion; intracellular phosphate ion homeostasis; phosphate ion transmembrane transport; sodium-dependent phosphate transport; arsenate ion transmembrane transport; cellular response to metal ion; cellular response to parathyroid hormone stimulus; cellular response to phosphate starvation; cellular response to staurosporine; dentinogenesis; kidney development; ossification; positive regulation of membrane potential; positive regulation of phosphate transmembrane transport; positive regulation of sodium-dependent phosphate transport; response to estradiol; response to growth hormone; response to magnesium ion; response to nutrient; response to parathyroid hormone; response to peptide; and 7 more
Cellular component: apical plasma membrane; plasma membrane; brush border; brush border membrane; vesicle; cell surface; endosome; membrane; perinuclear region of cytoplasm
Genetic constraint (gnomAD): Loss-of-function variants: 59 observed, 56.92 expected, observed/expected ratio (o/e) 1.04, 90% interval 0.84 to 1.29. The upper end of that interval is the gene's LOEUF score, 1.29, which puts it in group 5 of 6, group 1 being the genes least tolerant of losing a copy. Missense variants: 796 observed, 874.44 expected, observed/expected ratio (o/e) 0.91, 90% interval 0.86 to 0.96. Synonymous variants: 368 observed, 376.27 expected, observed/expected ratio (o/e) 0.98, 90% interval 0.9 to 1.07.
Gene-disease validity (ClinGen):
ClinGen rates the evidence that SLC34A1 causes each of these diseases.
hypercalcemia, infantile, 2 (autosomal recessive): Definitive. Any hypercalcemia, infantile in which the cause of the disease is a mutation in the SLC34A1 gene.
Fanconi renotubular syndrome 2 (autosomal recessive): Disputed. Any Fanconi syndrome in which the cause of the disease is a mutation in the SLC34A1 gene.
Homologues: Orthologues: macaque SLC34A1 (97% identical), chimpanzee SLC34A1 (92% identical), pig SLC34A1 (92% identical), dog SLC34A1 (91% identical), mouse Slc34a1 (91% identical), rat Slc34a1 (91% identical), guinea pig SLC34A1 (91% identical), rabbit SLC34A1 (90% identical), zebrafish slc34a1a (60% identical), zebrafish slc34a1b (58% identical), tropical clawed frog slc34a2 (54% identical), Caenorhabditis elegans ZK563.2 (28% identical). Paralogues in human: SLC34A2 (55% identical), SLC34A3 (46% identical).
Diseases named in the same sentence as SLC34A1 in open-access papers:
SLC34A1 is named in the same sentence as 63 diseases in open-access papers, as found by Europe PMC text mining. Sharing a sentence is not in itself a finding about the gene and the disease. The quoted sentences say what the papers report.
hypophosphatemia (27 papers, 2008 to 2025). Lower than normal levels of phosphates in the circulating blood. "Carriers of biallelic SLC34A1 variants had often hypophosphatemia, hyperphosphaturia (or decreased TmP/GFR or TRP), elevated calcitriol, and hypercalciuria with failure to thrive, bone manifestations, and nephrocalcinosis/-lithiasis." (PMID 40357590, 2025). "Loss of function variants of SLC34A1 result in decreased phosphate reabsorption in the renal tubule with resulting hypophosphatemia which decreases FGF23." (PMID 40765620, 2025). "IIH patients with biallelic SLC34A1 loss of function variants present mostly with hyperphosphaturia, hypophosphatemia, and subsequently elevated calcitriol levels with hypercalcemia, hypercalcuria, and nephrocalcinosis or -lithiasis." (PMID 40357590, 2025). "Infantile hypercalcemia 2 (OMIM phenotype number 616963) is an AR condition due to inactivating variants in SLC34A1, resulting in loss of NPT2a activity and subsequent renal phosphorus wasting with hypophosphatemia." (PMID 38606357, 2024). "This disease is also due to a defect in a sodium-dependent phosphate transporter located in the proximal tubules (in this case NaPi2a encoded by SLC34A1) resulting in hypophosphatemia, suppressed FGF23 levels and excessive 1,25(OH)2D levels." (PMID 35352187, 2022). "In contrast, inactivating mutations in SLC34A1 or SLC34A3 in humans are both associated with hypophosphatemia and nephrolithiasis." (PMID 34071837, 2021). "Consistently, global Slc34a1 knockout mice manifest hypophosphatemia and hyperphosphaturia associated with hypercalcemia and hypercalciuria all of which are known to influence bone mass." (PMID 33718388, 2021). "Our report of an autosomal dominant hypophosphatemia pedigree with 5 mutant carriers enriches the clinical phenotype caused by the SLC34A1 mutations and further affirms the heterozygous mutations are causative for hypophosphatemia." (PMID 31096470, 2019). "Currently, the relationship between heterozygous mutations in SLC34A1 and hypophosphatemia is controversial." (PMID 31096470, 2019). "A decreased activity of FGF-23 due to SLC34A1 mutation and subsequent hyperphosphaturia and hypophosphatemia, indirectly stimulate synthesis of 1,25(OH)2D that may produce hypercalcemia, hypercalciuria and nephrocalcinosis." (PMID 29904370, 2018). "It was reported that mutations in SLC34A1 gene may cause hypophosphatemia and urinary phosphate loss in patients with nephrolithiasis or osteoporosis." (PMID 28361944, 2017). "The patient’s father carried both the SLC34A1 and SLC34A3 mutations in heterozygosis, he had hypophosphatemia but was asymptomatic." (PMID 40943461, 2025). "Combined with the patient’s hypercalcemia and hypophosphatemia, heterozygous c.1726T > C in SLC34A1 is considered responsible for IIH." (PMID 38504242, 2024). "Seven patients diagnosed with hypercalcemia had a variant in heterozygous state in genes associated with hypophosphatemia (SLC34A3, SLC34A1, and SLC9A3R1 genes)." (PMID 38586466, 2024). "In our cohort, only 2 patients with biallelic variations in SLC34A3 (class V) or SLC34A1 (class III) presented with hypophosphatemia." (PMID 34721296, 2021). "Hypophosphatemia and nephrocalcinosis is due to mutations in the SLC34A1 gene encoding for NaPi2a." (PMID 34910242, 2022). "In 2016, mutations in SLC34A1, encoding the renal phosphate transporter NPT2a, were reported as the cause of Infantile Hypercalcemia type 2 (IH2) (MIM 616963) with renal phosphate wasting and hypophosphatemia." (PMID 34721296, 2021). "Thus, a major role of SLC34A1 is to facilitate reabsorption of glomerular-filtered phosphate in the proximal tubule, with disruption of this transporter leading to hypophosphatemia." (PMID 33718388, 2021). "Not in all patients with biallelic pathogenic variants in SLC34A1 and SLC34A3 can hypophosphatemia be observed." (PMID 41008628, 2025).
hypophosphatemia (continued). "The recent study of a family who displayed heterozygous inactivating mutations of SLC34A1 and SLC34A3 with severe hypophosphatemia and rickets supports the synergic and non-redundant action of SLC34A1 and SLC34A3 on renal phosphate transport." (PMID 34071837, 2021). "Similarly, 2/4 relatives carrying a SLC34A1 class III variation presented biochemical changes, 1 having a high urinary calcium excretion and 1 having hypophosphatemia (<-2 Z-score)." (PMID 34721296, 2021).
nephrolithiasis (23 papers, 2015 to 2026). The presence of a calculus in the pelvis of the kidney; this is most often composed of mineral salts and proteins. "Monoallelic variants of other genes, such as CYP24A1 and SLC34A1, have also been proven to have a role in increasing the risk of kidney stones." (PMID 40428323, 2025). "More recently, heterozygous SLC34A1 mutations have been associated with development of kidney stones or hypophosphatemic kidney stones with osteoporosis, even if often in the absence of functional verification." (PMID 40225330, 2025). "In 2012, a GWAS in a Japanese population identified SLC34A1 as a novel locus associated with nephrolithiasis." (PMID 35910217, 2022). "In a GWAS of nephrolithiasis in Japanese population, SNP rs11746443, located upstream of SLC34A1 gene, was identified as one of the three novel susceptible nephrolithiasis loci." (PMID 28361944, 2017). "In the replication study, rs12654812, located near SLC34A1, showed significant association with nephrolithiasis." (PMID 28361944, 2017). "Nine variants located in or near SLC34A1 show genome-wide significant association with kidney stones and correlate with the index variant rs12654812 (r2>0.63)." (PMID 26272126, 2015). "The association data presented here point to SLC34A1 as the kidney stone target at this locus." (PMID 26272126, 2015). "Pathogenic variants in the SLC34A1 gene, which encodes the sodium-phosphate cotransporter NaPi-IIa, lead to a spectrum of renal tubular disorders, including infantile hypercalcemia type 2, nephrolithiasis/osteoporosis-hypophosphatemia type 2, and Fanconi renotubular syndrome type 2." (PMID 41543768, 2026). "Both IIH and HHRH were originally described as autosomal-recessive disorders; however, heterozygous mutations in SLC34A1 and SLC34A3 seem to be associated with an increased risk to develop nephrolithiasis in adults." (PMID 40943461, 2025). "Pathogenic variants in the SLC34A1 gene have been associated with infantile hypercalcemia type 2 (OMIM, #616963) and nephrolithiasis/osteoporosis hypophosphatemic type 1 (OMIM, #612286)." (PMID 38586466, 2024). "Among those, we found rare missense variants at highly conserved sites in SLC34A1 and TRPV5 associating strongly with risk of kidney stones and recurrent kidney stones." (PMID 26272126, 2015). "We screened the kidney stones associated variants for their association to serum level of biochemical traits and detected association of variants at ALPL with ALP, SLC34A1 with PTH, and creatinine, phosphate and CLDN14 with PTH, magnesium and potassium." (PMID 26272126, 2015). "However, many SLC34A1 and SLC34A3 monoallelic carriers appear to have a lower TmP/GFR, elevated calcitriol levels, hypercalciuria, and a higher risk to develop kidney stones than the general population [61▪▪,62]." (PMID 40357590, 2025). "Notably, some patients with loss-of-function variants in SLC34A1 progressed early to CKD which has been attributed to nephrocalcinosis and kidney stones." (PMID 40357590, 2025). "Focusing our analysis on coding sequence variants in 63 genes with preferential kidney expression we identify two rare missense variants SLC34A1 p.Tyr489Cys (OR=2.38, P=2.8 × 10−5) and TRPV5 p.Leu530Arg (OR=3.62, P=4.1 × 10−5) associating with recurrent kidney stones." (PMID 26272126, 2015). "In addition to SLC34A1 p.Tyr489Cys, we found a rare missense variant in TRPV5 (NP_062815.2:p.Leu530Arg (MAF=0.13 %) associating significantly with recurrent kidney stones (OR=3.62, P=4.1 × 10−5<0.05/220=2.3 × 10−4)." (PMID 26272126, 2015). "Pathogenic variants in the SLC34A1 gene may cause a range of clinical phenotypes, including infantile hypercalcemia type 2 (IH2) (Omim: 616,963), nephrolithiasis/osteoporosis-hypophosphatemia type 2 (NPHLOP2) (Omim: 612,286), and Fanconi renotubular syndrome type 2 (Omim: 613388)." (PMID 41543768, 2026).
nephrolithiasis (continued). "Our results elucidated the significance of genetic variation at WDR72, DGKH, CLDN14, SLC34A1, and HIBADH in Chinese patients with nephrolithiasis." (PMID 35910217, 2022). "Finding of variants in the genes SLC34A1, SLC34A3 and SLC9A3R1 is not uncommon in patients with renal phosphate leak and kidney stones." (PMID 36596813, 2023).
Hypercalciuria (18 papers, 2017 to 2026). "Our findings expand the mutational and phenotypic spectrum of SLC34A1-related disease and reinforce the utility of oral phosphate supplementation in managing hypercalciuria and promoting growth." (PMID 41543768, 2026). "Haploinsufficiency of SLC34A1 is implicated in dysregulated phosphate and calcium homeostasis, predisposing to hypercalciuria and nephrocalcinosis." (PMID 41303235, 2025). "A monoallelic variant of CYP24A1 or SLC34A1 gene contributes to symptomatic hypercalcemia, hypercalciuria and nephrocalcinosis." (PMID 38504242, 2024). "Patients harboring SLC34A1 mutations typically present with hypophosphatemia and hypercalciuria." (PMID 41543768, 2026). "Moreover, we emphasize the therapeutic value of oral phosphate supplementation in mitigating long-term complications associated with hypercalciuria, a frequent and clinically significant feature in patients with SLC34A1-related disorders." (PMID 41543768, 2026). "In conclusion, we suggest that molecular testing for CYP24A1 and SLC34A1 mutations should be performed in each case of idiopathic hypercalcemia/hypercalciuria, both in children and adults, to determine the proper way for acute treatment and complications prevention." (PMID 28470390, 2017). "Biallelic loss-of-function variants in SLC34A1 and SLC34A3 cause two rare phosphate-wasting tubulopathies: idiopathic infantile hypercalcemia (IIH) and hereditary hypophosphatemic rickets with hypercalciuria, respectively." (PMID 40943461, 2025). "Different monogenic polymorphisms have been proposed as playing a causal role for calcium nephrolithiasis, including the VDR gene, CYP24A1, and SLC34A1; however, the complete pathogenetic pathway of hypercalciuria is yet to be determined." (PMID 34959915, 2021). "Loss-of-function variants in SLC34A1 and SLC34A3 are the cause of two rare phosphate-wasting disorders, idiopathic infantile hypercalcemia type 2 (IIH, OMIM #616963) and hereditary hypophosphatemic rickets with hypercalciuria (HHRH, OMIM #241530), respectively." (PMID 40943461, 2025).
nephrocalcinosis (17 papers, 2015 to 2025). Nephrocalcinosis is a disorder that occurs when too much calcium is deposited in the kidneys. "The first was just outside the canonical splice site (c.1175-3C > A) of SLC34A1 and validated by minigene assay which, together with a second variant c.241dup p.(Glu81fs), confirmed the diagnosis of nephrocalcinosis in this patient." (PMID 37946251, 2023). "Mutations of CYP24A1 and SLC34A1 are known to cause infantile hypercalcemia (IH) types 1 and 2, respectively, which are autosomal recessive disorders of calcium and phosphate metabolism associated with nephrocalcinosis and KSD." (PMID 40372791, 2025). "Interestingly, mutations in Slc34a1 have been linked to nephrocalcinosis and Fanconi renotubular syndrome." (PMID 34789782, 2021). "Additionally, their parents carrying the SLC34A1 mutation were also found having nephrocalcinosis." (PMID 38504242, 2024).
Hypercalcemia (13 papers, 2017 to 2026). An abnormally increased calcium concentration in the blood. "Consistent with findings from a recently published study we observed that patients harboring biallelic SLC34A1 variants typically presented at an earlier age, likely due to manifestations of infantile hypercalcemia." (PMID 41543768, 2026). "In contrast, the SLC34A1 alterations trigger hypercalcemia because of primary renal phosphate loss followed by an improper activation of vitamin D." (PMID 40943461, 2025). "In humans, the alterations caused by mutations in SLC34A1 are detected already in infants with idiopathic infantile hypercalcemia (IIH)." (PMID 35414099, 2022). "In the SLC34A1 defect, hypercalcemia is a sequel of primary loss of phosphate in the kidney followed by downregulation of FGF-23, which in-turn leads to increased vit." (PMID 28470390, 2017). "However, biallelic mutations in the CYP24A1 and SLC34A1 genes have a completely different mechanism leading to hypercalcemia." (PMID 40943461, 2025). "Our patients with monoallelic SLC34A1 variant also presented with symptomatic hypercalcemia." (PMID 38504242, 2024). "Autosomal recessive mutations in SLC34A1 can lead to idiopathic infantile hypercalcemia." (PMID 36978048, 2023). "In addition to the classic biochemical features associated with IIH of hypercalcaemia, hypercalciuria and high levels of 1,25-dihydroxyvitamin D3, patients with SLC34A1 loss-of-function mutations exhibit hypophosphatemia." (PMID 31935940, 2020). "The initial targeted NGS (next generation sequencing) panel included two genes implicated in idiopathic infantile hypercalcemia and phosphate–vitamin D metabolism: CYP24A1 and SLC34A1." (PMID 41303235, 2025). "Although the reported data are not sufficient for a final evaluation of the genetic mode of CYP24A1 and SLC34A1-related hypercalcemia, clinical evaluation and long-term observation are important for patients carrying monoallelic variants." (PMID 38504242, 2024). "Autosomal recessive inheritance of mutations in the sodium-phosphate co-transporter NaPi2a, encoded by SLC34A1, cause idiopathic infantile hypercalcaemia (IIH), classified as hypercalcaemia, infantile 2 (HCINF2), in a subgroup of patients without CYP24A1 mutations." (PMID 31935940, 2020). "We recommended studying the genes associated with genetic rickets (SLC34A1, SLC34A3, and SLC9A3R1) in those patients with hypercalcemia of suspected genetic cause but without a confirmatory genetic diagnosis, because they could have a heterozygous pathogenic variant." (PMID 38586466, 2024).
infantile hypercalcemia (11 papers, 2015 to 2025). "Autosomal recessive mutations in SLC34A1 are known to cause infantile hypercalcemia (IH) type 2, a condition that typically presents in early infancy." (PMID 41303235, 2025). "Infantile hypercalcemia is an autosomal recessive disorder caused either by mutations in the CYP24A1 gene (20q13.2) or in the SLC34A1 gene (5q35.3)." (PMID 33952337, 2021). "SLC34A1 mutation also causes autosomal-recessive infantile hypercalcemia-2 (HCINF2, MIM 616963) due to renal phosphate wasting-induced overproduction of 1,25(OH)2D3." (PMID 29505567, 2018). "Biallelic pathogenic SLC34A1 is related to infantile hypercalcemia-2 (HCINF2; #616963)." (PMID 41008628, 2025).
hyperphosphatemia (9 papers, 2008 to 2024). Abnormally high level of phosphate in the blood. "Slc34a1-Cre;αKlothoflox/flox mice showed weak hyperphosphatemia consistent with αKlotho deletion and significantly increased Npt2a mRNA expression." (PMID 29720668, 2018).